SPOP (speckle type BTB/POZ protein)
Diseases named in the same sentence as SPOP in open-access papers (continued):
Sharing a sentence is not in itself a finding about the gene and the disease.
prostate carcinoma (continued). "Cancer Genome Atlas (TCGA) analysis using 333 primary prostate carcinomas revealed that mutant SPOP-bearing tumors have the highest levels of AR-induced transcripts, indicating that upregulation of AR pathway is the most significant outcome of SPOP inactivation in PCa." (PMID 33158056, 2020). "The vast majority of prostate cancer-associated SPOP mutations identified so far affect evolutionarily conserved residues in the MATH domain, suggesting that these mutations may alter the interaction between SPOP and its substrates." (PMID 31771591, 2019). "Recently, some have used deep CNNs to predict whether or not SPOP was mutated in prostate cancer, given only the digital whole slide after standard H&E staining." (PMID 31632973, 2019). "Interestingly, a recent study provided evidence that SPOP-mutant prostate cancers failed to promote PD-L1 degradation due to their deficiency in binding to PD-L1 and promoting poly-ubiquitination." (PMID 31366128, 2019). "Applying these SRM assays to analyze HEK293T cells with and without expression of the three most frequent SPOP mutations in prostate cancer (Y87N, F102C or F133V) led to confident detection of all three SPOP mutations in corresponding positive cell lines but not in the negative cell lines." (PMID 28810879, 2017). "However, it remains unclear if mutant SPOP proteins can be utilized as biomarkers for early detection, diagnosis, prognosis or targeted therapy of prostate cancer." (PMID 28810879, 2017). "Indeed, deletion of the NLS sequence totally abolished the interaction between SPOP(WT, F125V, F133L) and overexpressed or endogenous KPNA5, suggesting that KPNA5 might participate in nuclear transport of wild-type and prostate cancer-associated SPOP mutants." (PMID 28448495, 2017). "In contrast, two prostate cancer-associated SPOP mutants lacking the NLS sequence (SPOP-F125V-ΔNLS, SPOP-F133L-ΔNLS) accumulated exclusively in the cytoplasm as puncta pattern similar as SPOP-ΔNLS, but these mutants did not co-localize with GFP-INF2, possibly due to impaired interaction with INF2." (PMID 28448495, 2017). "In an analysis of 333 individual prostate cancer exomes, TCGA identified seven subtypes defined either by gene fusions involving the ETS family (59% of cases), specifically ERG, ETV1, ETV4, or FLI1, or recurrent mutations (15% of cases) in SPOP, FOXA1, or IDH1." (PMID 28423598, 2017). "However, the low autoantibody level in the corresponding serum sample and the rare frequency of SPOP mutations in the study cohort indicate no crucial importance of mutations on serum-autoantibody levels in prostate cancer." (PMID 26863016, 2016). "Thus, these SPOP mutants could enhance AR functions in prostate cancers by inhibiting the turnover of both AR and its coactivator SRC-3." (PMID 27200299, 2016). "Importantly, prostate cancer-associated SPOP mutants fail to target AR for ubiquitination, whereas AR splicing mutants lacking hinge domain are refractory to SPOP-mediated degradation." (PMID 27200299, 2016). "To test if SPOP mutation also sensitizes to PARP inhibition, we treated MPCs (control vs tamoxifen-induced SPOP-F133V) with olaparib followed by IR—expression of SPOP-F133V increased sensitivity to olaparib similar to loss of SPOP in human prostate cancer cell lines." (PMID 26374986, 2015). "Additionally, we showed that the antiandrogen enzalutamide enhances SPOP-mediated degradation of full-length AR, but not most AR variants in prostate cancer cells." (PMID 24508459, 2014). "The spotlight in prostate cancer research has shifted to a protein with a seemingly innocuous acronym, Speckle-type POZ protein (SPOP), due to its profound influence on AR pathway regulation." (PMID 40432836, 2025). "Impaired binding of SPOP mutants to the ATF2 protein leads to reduced proteasomal degradation and subsequent accumulation of ATF2 in prostate cancer cell lines and specimens." (PMID 40771930, 2025).
prostate carcinoma (continued). "The E3 ligase SPOP regulates lipid metabolism by reducing FASN expression and fatty acid synthesis, leading to suppression of prostate cancer growth." (PMID 39944823, 2025). "Studies have shown that SPOP plays a key role in cancers such as RCC, hepatocellular carcinoma, prostate cancer, and lung cancer." (PMID 41122967, 2025). "Interestingly, the A646D mutation is reported to reduce AR:SPOP affinity and is frequently observed in patients with partial androgen insensitivity syndrome (PAIS), mild androgen insensitivity syndrome (MAIS), and prostate cancer (COSMIC legacy identifier- COSM6906185)." (PMID 38667288, 2024). "Genome sequencing studies have identified recurring founder mutations within the substrate-binding cleft of speckle-type POZ protein (SPOP), a cullin-RING ubiquitin ligase adaptor, in about 10% of primary prostate cancers." (PMID 39160596, 2024). "In prostate cancer cells with TRABID overexpression, however, high-level expression of TRABID overrides SPOP-mediated 53BP1 polyubiquitination, which consequently prolongs 53BP1 retention at DSB sites and inhibits HR activity." (PMID 37002234, 2023). "PXN expression was relatively high in ERG1- and FLI1-fusion-positive prostate cancers and SPOP-mutant prostate cancer, but it was relatively low in ETV1- and ETV4-fusion-positive prostate cancers." (PMID 36289913, 2022). "A study reported that AMPK promotes Speckle‐type POZ protein (SPOP)‐mediated NANOG ubiquitination and degradation in prostate cancer." (PMID 36114703, 2022). "Fortunately, cancer driver genes in prostate cancer, ERG, ETV1, ETV4, SPOP, and FOXA1, have been identified and their roles have been proved through basic and clinical research." (PMID 36579559, 2022). "However, the TCGA data show that none of these genes are downregulated in SPOP-mutated prostate cancer patient samples, and the mRNA levels of these genes are negatively correlated to SPOP mRNA expression in prostate cancers." (PMID 34599168, 2021). "In prostate cancer, as a key upstream regulator of TRIM24, TRIM28 was proved to interact with TRIM24 to prevent its ubiquitination and degradation by SPOP and also enhance the signal transduction of Androgen receptor (AR)." (PMID 33817325, 2021). "In contrast, we show here that mutually exclusive prostate cancer driver alterations involving the ERG transcription factor and the ubiquitin ligase adaptor SPOP are synthetic sick." (PMID 33531470, 2021). "This may provide a theory basis for prostate cancer treatment that involves relocalizing SPOP to nuclear speckles by decreasing its saturation concentration or inventing substrate motifs compatible with SPOP, thereby restoring LLPS and the ubiquitination balance to inhibit tumor progression." (PMID 34235141, 2021). "The most prominent role among the enzymes involved in ubiquitination in prostate cancer has been described for speckle-type poxvirus and zinc finger (POZ) protein (SPOP) that functions as a substrate adaptor of a CRL3." (PMID 33572160, 2021). "A recent study showed that PD-L1 abundance on prostate cancer cells is regulated by cyclin D. CDK4-mediated phosphorylation of SPOP and the cyclin 3-SPOP E3 ligase via proteasome-mediated degradation." (PMID 31366128, 2019). "SPOP directly interacts with CYCLIN E1 and specific regulates its stability in prostate cancer cell lines." (PMID 30237511, 2019). "Here, the authors show that TRIM28 interacts with TRIM24 to prevent SPOP-mediated ubiquitination of TRIM24 and enhances TRIM24 and AR signaling to induce prostate cancer tumorigenesis." (PMID 30479348, 2018). "Taken together, the study provides novel insights into the aberrant regulation of ATF2 in prostate cancer, showing that ATF2 is an important mediator of SPOP inactivation-induced cell proliferation, migration and Invasion." (PMID 29996942, 2018).
prostate carcinoma (continued). "Mutant SPOP fails to effectively ubiquitinate AR, resulting in increased AR protein stability and enhanced transcriptional activity, contributing to prostate cancer progression." (PMID 40432836, 2025). "SPOP has been reported to specifically interact with ERG, promoting its ubiquitination and degradation through WT-SPOP, which negatively regulates ERG-mediated prostate cancer cell migration and invasion." (PMID 40771930, 2025). "In addition to common essential genes, genes with known relevance to prostate carcinoma pathobiology, including AR, FOXA1, HOXB13, GATA2, SPOP, and AKT, were depleted." (PMID 40956611, 2025). "Mutant SPOP enhances TRIM24 stability, which in turn drives prostate cancer cell growth." (PMID 39160596, 2024). "Other genes associated with tumorigenesis of prostate cancer, such as ATM, MKI67, and SPOP, showed non-significant increases in somatic mutation frequency in the low-TICS group." (PMID 36918939, 2023). "For example, PXN, which is known as an oncogene in prostate cancer, has higher expression in the ERG and SPOP subtypes of prostate cancer, as compared to normal cells, and lower expression in ETV1 and ETV4 subtypes of prostate cancer, as compared to normal cells." (PMID 36289913, 2022). "Mutation in the tumor suppressor SPOP and negative regulator of NANOG also leads to increased stemness of prostate cancer and a negative prognosis in prostate cancer." (PMID 35205716, 2022). "It is mutually exclusive with other alterations including SPOP and CHD1 loss of function, indicating that TMPRSS2‐ERG negative prostate cancers progress by different tumorigenic processes or represent different cellular subtypes." (PMID 35347810, 2022). "In addition, in SPOP-null C4-2B prostate cancer cells, the turnover rate (half-life) of G3BP1 remains unchanged compared with the parental SPOP-wt C4-2B cells." (PMID 34795264, 2021). "Finally, we confirmed that the expression of mutant SPOP prolonged the half-life of endogenous ZMYND11 in VCaP cells and upregulated ZMYND11 expression in other prostate cancer cells." (PMID 33531470, 2021). "In agreement with recent reports, lentiviral-transduced point mutants of SPOP (SPOP-Y87C, SPOP-W131G) or a truncated version of ERG, which typically results from gene fusion with androgen-regulated genes in prostate cancer (ΔERG, amino acids 33–486), promoted cell growth 13–16." (PMID 33531470, 2021). "Indeed, similar to the known SPOP substrate ERG, the protein abundance of ABL1 increased in DU145 prostate cancer cells upon treatment with either the proteasome inhibitor MG132 or the neddylation inhibitor MLN4924." (PMID 34795215, 2021). "Forced expression of mutant SPOP (SPOP-Y87C, SPOP-W131G) promoted 3D growth of ERG fusion-negative LAPC-4 human prostate cancer cells." (PMID 33531470, 2021). "In this study we not only reveal the tumor suppressive role of SPOP by targeting PDK1 for degradation and AKT inactivation, but also highlight combating PDK1-AKT pathway as a potent strategy to treat SPOP mutant-driven prostate cancer." (PMID 34353330, 2021). "To address this question, we examined DNA breaks in SPOP-depleted, normally growing, prostate cancer cells in the absence of any exogenous DNA damage stress." (PMID 33023230, 2020). "Studies of the roles of SPOP and PIN1 in prostate cancer stemness and progression have revealed that PIN1 is an upstream regulator of NANOG and also protects the latter from SPOP-mediated polyubiquitination and degradation, thus promoting NANOG-conferred cancer stemness features in prostate tumors." (PMID 32268506, 2020).
prostate carcinoma (continued). "As expected, depletion of SPOP or expression of an F133V mutant suppressed HDR and instead enhanced NHEJ after introduction of DSBs by gamma irradiation or camptothecin treatment in prostate cancer cells and primary prostate epithelial cells." (PMID 33023230, 2020). "Besides, the protein level of BRD4 has a significant effect on BET inhibitors, and this process is regulated by the activity of SPOP, which degrades BRD4 in prostate cancer cells." (PMID 31718704, 2019). "The normal SPOP protein, but not the mutants observed in prostate cancer, is able to interact with SRC-3 and promote its ubiquitination and degradation." (PMID 31366128, 2019). "In human prostate cancer organoids and xenograft models, we further showed that a selective HDAC3 inhibitor is efficacious in inhibition of AKT and AR signaling in both PTEN‐ and SPOP‐mutant background." (PMID 29523594, 2018). "Here, we used human prostate cancer samples and showed that the vast majority of human SPOP-mutant cancers do not express ERG." (PMID 29202479, 2018). "SPINK1 is commonly overexpressed in SPOP-mutant and other ETS-negative prostatic cancers." (PMID 29581876, 2018). "Expression of mutant SPOP activates PI3K/AKT pathway and upregulates AR signaling, maintaining AR transcriptional activity against PI3K/AKT‐mediated negative feedback, effectively activating the two most common driver pathways critical in prostate cancer." (PMID 29572264, 2018). "Recurrent SPOP mutants stabilize TRIM24, enhancing AR signaling and promoting tumor growth via binding with the proteins TIP60 and BRD7, which has led to the proposition of TRIM24 as an essential gene for prostate cancer cell proliferation in CRPC." (PMID 29888169, 2018). "Next, we decided to extend our analysis by investigating whether endogenous SPOP and INF2 can interact with each other in prostate cancer cells." (PMID 28448495, 2017). "This effort led to the successful generation of seven novel organoid lines harboring prostate-cancer-specific driver alterations, including ETS-translocations, CHD1 loss, and SPOP and FOXA1 mutations-three of which had not been previously represented in 2D prostate cancer cell line models." (PMID 38835365, 2024). "The dominant‐negative effects of SPOP mutant proteins on different substrate proteins may correspond to the occurrence and progression of endometrial and prostate cancers." (PMID 36259278, 2022). "Analyses of The Cancer Genome Atlas and the Canadian Prostate Cancer Genome Network support that prostate cancers with cribriform architecture have increased genetic instability and copy number alterations with frequent genetic alterations to known drivers of prostate cancer including PTEN and SPOP." (PMID 33600062, 2021). "Whether or not pBRD4 is increased as a result of SPOP mutation, and if SPOCK1 induction mediates the increased PI3K/AKT signaling in prostate cancer is unknown." (PMID 33712563, 2021). "Interestingly, SPOP mutant prostate cancers lacked EGR rearrangements and exhibited a peculiar pattern of genomic alterations, thus suggesting that they form a molecular subtype of prostate cancer." (PMID 31366128, 2019). "Somatic heterozygous missense mutations occurring at the level of the substrate-binding cleft of speckle-type PO2 protein (SPOP) gene were identified in up to 15% of human prostate cancers, thus making SPOP the gene most commonly affected by nonsynonymous point mutation in this cancer." (PMID 31366128, 2019).
prostate carcinoma (continued). "Moreover, we found that ectopic expression of SPOP in LNCaP or DU145 prostate cancer cells did not alter the protein level of endogenous INF2." (PMID 28448495, 2017). "However, our preliminary results found that hypoxia treatment did not affect SPOP localization at least, in prostate cancer cells." (PMID 28448495, 2017). "This study showed that in LHMAR and LNCaP cell lines, SPOP mutant-related or vector-based overexpression of DEK significantly promotes cell invasion and knockdown of DEK decreases cell invasion of cells overexpressing mutant SPOP, which implicates DEK as an oncogenic effector in prostate cancer." (PMID 25544761, 2015). "These two studies also reported mutated genes (SPOP and CHD1) that may define prostate cancer subtypes which are ETS gene family fusion negative." (PMID 23957008, 2013).